MTBP (MDM2 binding protein)
Description:
Inhibits cell migration in vitro and suppresses the invasive behavior of tumor cells (By similarity). Inhibits autoubiquitination of MDM2, thereby enhancing MDM2 stability.
Synonyms: MDM2BP
Tractability: PROTAC: ubiquitination databases record sites on it.
Gene: Protein-coding gene on chromosome 8 (120,445,400 to 120,542,133, forward strand). Ensembl gene ENSG00000172167.
Subcellular location (Human Protein Atlas): Nucleoplasm; Nuclear bodies
Pathways (Reactome):
Cell-Cell communication: Degradation of CDH1
Gene Ontology:
Biological process: protein localization to kinetochore; traversing start control point of mitotic cell cycle; regulation of protein ubiquitination
Cellular component: chromatin; kinetochore
Genetic constraint (gnomAD): Loss-of-function variants: 47 observed, 58.28 expected, observed/expected ratio (o/e) 0.81, 90% interval 0.64 to 1.03. The upper end of that interval is the gene's LOEUF score, 1.03, which puts it in group 4 of 6, group 1 being the genes least tolerant of losing a copy. Missense variants: 582 observed, 637.29 expected, observed/expected ratio (o/e) 0.91, 90% interval 0.85 to 0.98. Synonymous variants: 211 observed, 233.24 expected, observed/expected ratio (o/e) 0.9, 90% interval 0.81 to 1.01.
Homologues: Orthologues: chimpanzee MTBP (99% identical), macaque MTBP (97% identical), pig MTBP (85% identical), dog MTBP (84% identical), rabbit MTBP (83% identical), rat Mtbp (78% identical), mouse Mtbp (77% identical), guinea pig MTBP (71% identical), tropical clawed frog mtbp (49% identical), zebrafish mtbp (42% identical).
Diseases named in the same sentence as MTBP in open-access papers:
MTBP is named in the same sentence as 23 diseases in open-access papers, as found by Europe PMC text mining. Sharing a sentence is not in itself a finding about the gene and the disease. The quoted sentences say what the papers report.
hepatocellular carcinoma (6 papers, 2018 to 2023). A malignant tumor that arises from hepatocytes. "Recently, a novel interaction between PXR and the MDM2-binding protein (MTBP) was described in different models of hepatocellular carcinoma." (PMID 34831358, 2021). "The MTBP gene with an associated MDM2 binding protein, is often overexpressed in human malignancies including triple negative breast cancer and is involved in suppression of invasive behavior of hepatocellular carcinoma." (PMID 37915799, 2023). "Specifically, our previous studies and others have demonstrated that MTBP suppresses migration and metastasis of osteosarcoma, gastric cancer, head and neck cancer, and hepatocellular carcinoma (HCC) cells." (PMID 37760565, 2023). "In this study, we demonstrate that the high level of MTBP’s endogenous expression is correlated with poor prognosis of advanced hepatocellular carcinoma (HCC) patients who received sorafenib." (PMID 34249768, 2021). "Increasing evidence indicates that the oncoprotein murine double minute (MDM2) binding protein (MTBP) can be considered a pro-oncogene of human malignancies; however, its function and mechanisms in hepatocellular carcinoma (HCC) are still not clear." (PMID 36106099, 2022).
breast carcinoma (5 papers, 2013 to 2023). "Furthermore, both PREX1 and MTBP have been previously implicated in breast cancer progression." (PMID 23972288, 2013). "Significantly, analysis of the TCGA dataset revealed that MTBP is amplified in 19% breast cancer, and its mRNA expression levels are notably elevated in TNBC relative to those in other subtypes of breast cancer." (PMID 38009308, 2023). "In breast cancer patients, both elevated MTBP mRNA expression (n = 842, p = 0.0337) and MTBP gene amplification (n = 913, p = 0.0195) independently predict poor patient survival." (PMID 35741402, 2022). "While our own efforts focused on TNBC, we also reported MTBP expression is elevated in estrogen receptor positive (ER+) breast cancers as well as those expressing the receptor tyrosine kinase human epidermal growth factor receptor 2 (HER2)." (PMID 35741402, 2022). "MTBP protein was also observed to be elevated in a panel of human breast cancer cell lines." (PMID 35741402, 2022). "Moreover, in breast cancer, MTBP mRNA levels were the highest in the aggressive and deadly triple negative breast cancer (TNBC) subtype, which has been reported to have a high MYC transcriptional signature." (PMID 35741402, 2022). "In breast cancer patients (n = 421) whose cancers have high levels of MYC mRNA expression, concurrent high expression of both MYC and MTBP mRNA conferred worse survival compared to those with high MYC and low MTBP expression (p = 0.0314)." (PMID 35741402, 2022).
glioblastoma (3 papers, 2019 to 2023). The most malignant astrocytic tumor (WHO grade IV). "A subsequent study in glioblastoma confirmed increased MTBP expression was associated with higher grade gliomas and poor patient outcomes." (PMID 35741402, 2022). "These analyses also demonstrated increased MTBP expression was associated with poor patient outcomes in glioblastomas (p = 7.344 × 10−5), gliomas (p = 4.4342 × 10−12 and 3.053 × 10−5), and renal cancer (p = 1.062 × 10−5)." (PMID 35741402, 2022). "On the other hand, MTBP expression appears to serve as a biomarker for poor prognosis in patients with glioblastoma and triple-negative breast cancer." (PMID 37760565, 2023). "The effects of reducing MTBP expression have also been examined in glioblastoma, where knockdown inhibited proliferation and neurosphere formation as well as induction of apoptosis." (PMID 35741402, 2022). "This same diametric effect on proliferation with reduced and increased MTBP expression was independently verified in HeLa, colon cancer, glioblastoma, and lung cancer cells." (PMID 35741402, 2022). "Here, elevated MTBP expression correlated with the Classical molecular subtype of glioblastoma, known to carry poorer outcomes than the Proneural molecular subtype." (PMID 35741402, 2022). "Interestingly, a similar sensitization to radiation was observed in glioblastoma cells following knockdown of MTBP." (PMID 35741402, 2022). "Interestingly, shRNA knockdown of MTBP sensitized glioblastoma xenografts to both radiation and the alkylating agent temozolomide, suggesting targeting MTBP could synergize with existing therapies." (PMID 35741402, 2022). "Collectively, these data indicate that targeting MTBP may provide therapeutic benefit, particularly in TNBC, glioblastoma, and lung cancer." (PMID 35741402, 2022).
osteosarcoma (3 papers, 2018 to 2023). A usually aggressive malignant bone-forming mesenchymal neoplasm, predominantly affecting adolescents and young adults.
B cell lymphomas (2 papers, 2019 to 2022). "This was first observed in lymphoma where Mtbp/MTBP was discovered to be overexpressed in primary murine B cell lymphomas as well as human B cell lymphoma cell lines." (PMID 35741402, 2022).
esophageal squamous cell carcinoma (2 papers, 2017 to 2023). Esophageal squamous cell carcinoma (ESCC) is a type of esophageal carcinoma (EC) that can affect any part of the esophagus, but is usually located in the upper or middle third. "Clinical studies also support that decreased MTBP levels are correlated with increased metastasis and/or poor prognosis in gastric cancer, head and neck cancer, esophageal squamous cell carcinoma, and HCC." (PMID 37760565, 2023). "Clinically, several studies using human cancer patients have suggested MTBP as a potential biomarker for favorable prognosis in patients with specific cancer types, including HNSCC, gastric cancer, and esophageal squamous cell carcinoma." (PMID 37760565, 2023).
glioma (2 papers, 2019 to 2022). A benign or malignant brain and spinal cord tumor that arises from glial cells (astrocytes, oligodendrocytes, ependymal cells). "In the case of TCGA gliomas, MTBP expression was associated with the histopathologic grade of glioma, with higher MTBP expression being observed in high-grade gliomas (P<0.001)." (PMID 31534534, 2019). "Moreover, compared with proneural, mesenchymal, and neural subtypes, MTBP expression was found to be significantly elevated in classical gliomas (P<0.001)." (PMID 31534534, 2019). "MTBP mRNA expression in clinical gliomas was examined using TCGA and REMBRANDT datasets." (PMID 31534534, 2019).
lung carcinoma (2 papers, 2022). "In a broader analysis of publicly available datasets, high MTBP mRNA expression was associated with worse survival for patients with lung cancer (p = 0.01011 and 1.745 × 10−5), consistent with the studies above." (PMID 35741402, 2022). "Knockdown of MTBP by shRNA or siRNA decreased proliferation of lung cancer cells and reduced colony formation of gastric adenocarcinoma cells, respectively." (PMID 35741402, 2022). "Furthermore, several studies have demonstrated the importance of MTBP in lung cancer." (PMID 35741402, 2022).
lymphoma (2 papers, 2016 to 2022). A malignant (clonal) proliferation of B- lymphocytes or T- lymphocytes which involves the lymph nodes, bone marrow and/or extranodal sites. "However, in human cancer, MTBP is amplified and/or overexpressed in a range of malignancies, including lymphomas, carcinomas, and sarcomas, suggesting it is oncogenic in multiple tissue types." (PMID 27803394, 2016).
triple-negative breast carcinoma (2 papers, 2023). An invasive breast carcinoma which is negative for expression of estrogen receptor (ER), progesterone receptor (PR), and human epidermal growth factor receptor 2 (HER2). "The MTBP gene may be involved in tumor formation and has been reported to be over expressed in triple negative breast cancer." (PMID 37915799, 2023).
colon cancer (1 paper, 2022). "MTBP mRNA and protein were reported to be overexpressed in a panel of human colon cancer cell lines as well as 60 primary colon cancer samples with matched normal controls (p < 0.01)." (PMID 35741402, 2022).
gastric adenocarcinoma (1 paper, 2022). "Additionally, MTBP was identified in a CRISPR-Cas9 screen as one of nine essential genes for gastric adenocarcinoma survival." (PMID 35741402, 2022).
lung adenocarcinoma (1 paper, 2022). A carcinoma that arises from the lung and is characterized by the presence of malignant glandular epithelial cells. "In an analysis of multiple datasets of stage I lung adenocarcinoma patients, MTBP expression was associated with decreased patient survival (p < 0.001, p = 0.001 and p = 0.037)." (PMID 35741402, 2022). "In a separate analysis of MTBP protein expression by immunohistochemistry in 112 lung adenocarcinoma patient samples spanning stage I to stage IV disease, “hyper-expression” of MTBP was observed in 23.21% of samples." (PMID 35741402, 2022). "Early-stage lung adenocarcinoma samples (n = 119) exhibited high MTBP mRNA compared to normal lung tissue (p = 0.0069)." (PMID 35741402, 2022).
cancer (12 papers, 2016 to 2025). A tumor composed of atypical neoplastic, often pleomorphic cells that invade other tissues. "The MDM2 binding protein MTBP is implicated in various cellular functions and cancer-related processes, which vary depending on the cellular context and its localization within the cell." (PMID 37760565, 2023). "We also discuss the role of MTBP in cancer, as MTBP levels are elevated in many human cancers and is often associated with reduced cancer patient survival." (PMID 35741402, 2022). "Consistent with its oncogenic role, MTBP has been shown to be overexpressed in a wide range of human cancers, where it is associated with poor patient outcomes in the majority of malignant contexts." (PMID 35741402, 2022). "We therefore predict that over- or under-expression of Treslin–MTBP causes defects in correct origin selection, providing an explanation for why MTBP is misregulated in certain cancers." (PMID 34699733, 2021). "Similarly, higher levels of MTBP are also associated with poor prognostic outcomes in various cancer types." (PMID 37533202, 2023). "MTBP is implicated in cell cycle progression, DNA replication, and cancer metastasis." (PMID 37760565, 2023). "This discovery provided critical context for data linking MTBP to aging as well as a rapidly expanding body of evidence demonstrating MTBP is overexpressed in many human malignancies, is often linked to poor patient outcomes, and is necessary for cancer cell survival." (PMID 35741402, 2022). "The regulation of MTBP in human cancer, despite its functional significance, remains largely unclear." (PMID 38009308, 2023). "Our investigations into a protein named MTBP revealed that it associates with MYC and helps its pro-growth and cancer promoting function." (PMID 35741402, 2022). "This was the first in vivo study to demonstrate the potential of MTBP as a therapeutic target in cancer." (PMID 35741402, 2022). "Beyond its molecular characterization, several groups have identified MTBP as an important protein in multiple human cancers." (PMID 35741402, 2022). "Moreover, in cell culture, MTBP increases proliferation when growth factors are limiting, suggesting that sustained or dysregulated MTBP expression could serve as a mechanism for cells to survive and proliferate with limited external growth signals, echoing a hallmark of cancer." (PMID 35741402, 2022). "Here we have reviewed the discovery of MTBP and the initial controversy with its function as well as its associations with proliferation, MYC, DNA replication, aging, and human cancer." (PMID 35741402, 2022). "A comprehensive analysis of data from The Cancer Genome Atlas (TCGA) indicated MTBP is amplified in at least 20 different types of human cancer." (PMID 35741402, 2022). "Recently, MTBP has been regarded as an important regulator of human cancer cells’ proliferation or metastasis." (PMID 34249768, 2021). "On the other hand, there are a few reports suggesting cancer-promoting roles of MTBP in leukemia and breast cancer by cooperating with Myc." (PMID 29765550, 2018). "MTBP is involved in diverse cellular functions and cancer-related processes." (PMID 37760565, 2023). "Given that the functional role of the top one down‐regulated protein LINGO2 (leucine rich repeat and Ig domain containing 2) following C9orf142 knockdown in human cancer is ambiguous, we selected MTBP, the second down‐regulated protein following C9orf142 knockdown, for further verification." (PMID 38009308, 2023). "As such, MTBP may represent an as yet untapped broadly applicable therapeutic target in human cancer, or an avenue to augment the effectiveness of existing therapies." (PMID 35741402, 2022). "Moreover, there are many other cancers that actively select for MTBP overexpression as well as cancers that rely on high MYC activity." (PMID 35741402, 2022). "Interestingly, even at the level of cancer patient survival, the observation that MTBP is a limiting factor for MYC oncogenic activity can be observed." (PMID 35741402, 2022).